BNIP3 (BCL2 interacting protein 3)
Description:
Apoptosis-inducing protein that can overcome BCL2 suppression. May play a role in repartitioning calcium between the two major intracellular calcium stores in association with BCL2. Involved in mitochondrial quality control via its interaction with SPATA18/MIEAP: in response to mitochondrial damage, participates in mitochondrial protein catabolic process (also named MALM) leading to the degradation of damaged proteins inside mitochondria. The physical interaction of SPATA18/MIEAP, BNIP3 and BNIP3L/NIX at the mitochondrial outer membrane regulates the opening of a pore in the mitochondrial double membrane in order to mediate the translocation of lysosomal proteins from the cytoplasm to the mitochondrial matrix. Plays an important role in the calprotectin (S100A8/A9)-induced cell death pathway.
Synonyms: NIP3; HABON
Tractability: Antibody: UniProt predicts a signal peptide or a membrane-spanning region. PROTAC: ubiquitination databases record sites on it; its protein half-life has been measured.
Gene: Protein-coding gene on chromosome 10 (131,966,461 to 131,981,984, reverse strand). Ensembl gene ENSG00000176171.
Subcellular location: Mitochondrion; Mitochondrion outer membrane
Gene Ontology:
Molecular function: endoplasmic reticulum-autophagosome adaptor activity; GTPase binding; identical protein binding; mitochondrion autophagosome adaptor activity; protein binding; protein homodimerization activity
Biological process: cellular response to cobalt ion; cellular response to hypoxia; cellular response to mechanical stimulus; defense response to virus; granzyme-mediated programmed cell death signaling pathway; intrinsic apoptotic signaling pathway in response to hypoxia; mitochondrial fragmentation involved in apoptotic process; mitochondrial outer membrane permeabilization; mitochondrial protein catabolic process; mitophagy; negative regulation of membrane potential; negative regulation of mitochondrial fusion; negative regulation of programmed cell death; positive regulation of apoptotic process; positive regulation of macroautophagy; positive regulation of mitochondrial fission; positive regulation of programmed cell death; positive regulation of protein-containing complex disassembly; positive regulation of release of cytochrome c from mitochondria; reactive oxygen species metabolic process; regulation of mitochondrial membrane permeability; reticulophagy; autophagy of mitochondrion; negative regulation of apoptotic process; neuron apoptotic process; and 16 more
Cellular component: endoplasmic reticulum membrane; mitochondrial membrane; mitochondrial outer membrane; mitochondrion; nuclear envelope; cytoplasm; dendrite; endoplasmic reticulum; nucleoplasm; nucleus; membrane; mitochondrial envelope; postsynaptic density
Genetic constraint (gnomAD): Loss-of-function variants: 13 observed, 18.87 expected, observed/expected ratio (o/e) 0.69, 90% interval 0.45 to 1.1. The upper end of that interval is the gene's LOEUF score, 1.1, which puts it in group 4 of 6, group 1 being the genes least tolerant of losing a copy. Missense variants: 185 observed, 220.3 expected, observed/expected ratio (o/e) 0.84, 90% interval 0.74 to 0.95. Synonymous variants: 74 observed, 78.61 expected, observed/expected ratio (o/e) 0.94, 90% interval 0.78 to 1.14.
Homologues: Orthologues: chimpanzee BNIP3 (100% identical), macaque BNIP3 (99% identical), guinea pig BNIP3 (94% identical), mouse Bnip3 (90% identical), rat Bnip3 (90% identical), dog BNIP3 (90% identical), rabbit BNIP3 (87% identical), tropical clawed frog bnip3 (79% identical), zebrafish bnip3 (66% identical), Drosophila melanogaster BNIP3 (29% identical), Caenorhabditis elegans dct-1 (26% identical). Paralogues in human: BNIP3L (62% identical).
Diseases named in the same sentence as BNIP3 in open-access papers:
BNIP3 is named in the same sentence as 225 diseases in open-access papers, as found by Europe PMC text mining. Sharing a sentence is not in itself a finding about the gene and the disease. The quoted sentences say what the papers report.
breast cancer (115 papers, 2005 to 2026). A primary or metastatic malignant neoplasm involving the breast. "In these studies, the authors showed that BNIP3 loss due to impaired receptor‐mediated mitophagy in murine breast cancer cells promoted malignancy resulting in higher accumulation of mitochondrial dysfunctions and increased oxidative stress." (PMID 39945227, 2025). "The expression of BNIP3 in different tumors is inconsistent, and its high expression in tumors such as lung cancer, prostate cancer, breast cancer, and endometrial cancer is associated with a bleak prognosis for patients diagnosed with tumors." (PMID 40837014, 2025). "In an MMTV‐PyMT mouse mammary tumor model, loss of BNIP3 promoted tumor growth and accelerated lung metastasis in vivo." (PMID 39472438, 2024). "Bcl-2 interacting protein 3 (BNIP3) has been associated with hypoxia, whose aberrant expression is involved in the carcinogenesis of breast cancer (BC)." (PMID 35200106, 2022). "In this work, the authors showed that BNIP3 deletion in murine breast cancer promoted malignancy caused by accumulation of dysfunctional mitochondria and by angiogenesis induced by the increased oxidative stress." (PMID 35459212, 2022). "Most recently, we and others identified that oxidized ATM has the potential to induce autophagosome accumulation and exosome release from hypoxic breast cancer-associated fibroblasts (CAFs) through phosphorylating BCL2-interacting protein 3 (BNIP3)." (PMID 34830956, 2021). "b Measurement of BNIP3 mRNA expression level by overexpression of YTHDF2 in FTO-deficient breast cancer cells." (PMID 30922314, 2019). "Examples can be sought in case of pancreatic cancer and some mammary tumors where loss of BNiP3 function leads to increased metastasis." (PMID 30697531, 2018). "In contrast to other studies, in breast cancer cells, BNIP3 deletion promotes metastasis and is linked with poor prognosis in human triple-negative breast cancer (TNBC)." (PMID 30250843, 2018). "In Tiaozhi granule components, flavonoid, extractor of Pollen Typhae Angustifoliae, has been demonstrated to induce autophagy via ROS-dependent mitochondrial dysfunction and loss of ATP involving BNIP3 in human MCF7 breast cancer cells." (PMID 30108646, 2018). "In some cases of breast carcinoma and prostate cancer, elevated levels of BNiP3 were associated with increased metastasis and poor prognosis." (PMID 30697531, 2018). "Exposure of MCF7 and MDA-MB-231 breast cancer cells to hypoxia caused a progressive increase in Bnip3 protein that started at 6 hrs of hypoxia and peaked at 24 hrs." (PMID 24811485, 2014). "BNIP3 expression is lost in a significant proportion of invasive breast cancers, and loss of BNIP3 expression correlated with poor prognostic features such as positive lymph node status and high proliferation, but not with the hypoxic response." (PMID 19505343, 2009). "Association between BNIP3 mRNA and protein expression and the hypoxia response proteins in invasive breast cancer (n = 40)." (PMID 19505343, 2009). "Interestingly, elevated BNIP3 levels in breast cancer cell lines (MCF7 and MDA-MB-231) have been linked to increased metabolic activity, cell proliferation, and migration." (PMID 40209344, 2025). "Interestingly, the loss of BNIP3 is associated with malignant progression in TNBC, and treating BNIP3-null cells with 2‐deoxyglucose (2DG) to inhibit glycolysis has been demonstrated to effectively suppress breast cancer growth in vitro." (PMID 39472438, 2024). "Also, other authors showed that BNIP3 loss increased angiogenesis, promoted tumor growth and breast cancer metastatization, due to the accumulation of dysfunctional mitochondria." (PMID 35459212, 2022). "In breast cancer, BNIP3 loss promoted tumor progression and metastasis." (PMID 31671556, 2019).
breast cancer (continued). "As a component of viral genome, we hypothesized that the presence of BNiP3 in addition to oncolytic nature of Edmonston strain of measles virus will cause induction of apoptosis, and cell death in breast cancer cells." (PMID 30697531, 2018). "The induction of autophagy through BNIP3 in pre-invasive breast cancers provides tumor cells with extra nutrients and promotes tumor progression." (PMID 40113750, 2025). "Although BNIP3 is often considered a protective gene that inhibits cancer growth, studies have shown that inhibiting BNIP3 gene expression leads to breast cancer progression." (PMID 41282023, 2025). "Our data indicated that BNIP3 consistently displayed significantly lower expression levels in breast cancer samples across various datasets, warranting further investigation." (PMID 40337509, 2025). "An associated study revealed that the activation of insulin-like growth factor 1 (IGF-1)/phosphoinositide 3-kinase (PI3K) signaling promotes BNIP3-mediated mitophagy in breast cancer." (PMID 39472438, 2024). "Overall, BNIP3 exhibits complex and context-dependent functions in breast cancer biology, and the specific functions of BNIP3 in breast cancer progression need further investigation." (PMID 39472438, 2024). "In a mouse mammary tumor model, BNIP3 has been found to prevent tumor cell proliferation and tumor growth." (PMID 39454000, 2024). "Lal and Rajala developed a recombinant measles virus carrying BNiP3, a pro-apoptotic gene of human origin, as an oncolytic agent and demonstrated its ability to induce apoptosis in breast cancer cells in vitro." (PMID 37009515, 2023). "HIF-1α is the principal regulator of hypoxia, and is also led to autophagy activation with BNIP3 in breast cancer." (PMID 36937439, 2023). "BNIP3 protein levels are upregulated at the early premalignant stages of various human solid cancers, including pancreatic cancer and breast cancer, but frequently decrease when these tumors become invasive." (PMID 38156294, 2023). "Lal and Rajala have developed a recombinant measles virus harboring BNiP3, a pro-apoptotic gene of human origin, which as an oncolytic agent, has been shown to induce apoptosis in breast cancer cells in vitro." (PMID 37009515, 2023). "The prognostic significance of BNIP3 in breast cancer patients was also investigated in the TCGA breast cancer cohort." (PMID 35912211, 2022). "FTO mediated m6A demethylation in a YTHDF2-dependent manner and promoted the proliferation and metastasis of breast cancer via inhibiting BCL2 interacting protein 3 (BNIP3)." (PMID 35721510, 2022). "Regulation of mitochondrial ROS production by BNIP3, a hypoxia-induced mitophagy regulator, suppresses breast cancer progression." (PMID 36284011, 2022). "FTO demethylates m6A in the 3′-UTR of BNIP3 and reduces its expression; this promotes the proliferation, colony formation, and metastasis of breast cancer cells." (PMID 35141221, 2022). "Similar to our findings in osteosarcoma, increased BNIP3 level has been reported to be correlated with an aggressive tumor phenotype and a poor prognosis in a number of cancers, including breast cancer, non-small cell lung cancer, and uveal melanoma." (PMID 36578780, 2022). "And the deletion of BNIP3 can increase angiogenesis which promotes tumorigenesis and the metastasis of breast cancer." (PMID 36092153, 2022). "On the contrary, it has been demonstrated that BNIP3 promoted the malignant phenotypes of breast cancer cells under hypoxia." (PMID 35912211, 2022). "Mechanistically, FTO exerted its oncogenic role in breast cancer via demethylating BCL2 Interacting Protein 3 (BNIP3), a pro-apoptosis member in the Bcl-2 apoptotic protein family." (PMID 35409166, 2022). "BNIP3 is highly expressed in prostate, lung, endometrial, and breast cancer, and HIF-1α can induce further expression." (PMID 36675706, 2022).
breast cancer (continued). "Gossypol upregulates apoptosis-promoting genes such as those involved in growth arrest and DNA damage-inducible 45 alpha (GADD45A), tumor necrosis factor receptor superfamily 9, and BCL2-interacting protein 3 in breast cancer cells." (PMID 35283426, 2022). "On the other hand, the m6A eraser, FTO was found to promote the degradation of BNIP3 and inhibited the proliferation and invasion of breast cancer cells." (PMID 35646049, 2022). "According to one study, the elevation of the ceramide level following fatty acid suppression can activate the expression of the proapoptotic protein, BNIP3, in breast cancer cells." (PMID 35243817, 2022). "Researchers reported that upregulated FTO enhanced the development and metastasis of breast cancer cell through downregulation of BCL2 interacting protein 3 (BNIP3) expression in both vitro and vivo experiment." (PMID 35937999, 2022). "Another study demonstrated the demethylase FTO promotes breast cancer progression by inhibiting BNIP3." (PMID 35197112, 2022). "The proportion of BNIP3-positive cells is higher in breast cancer cells as compared to normal breast epithelial cells." (PMID 35912211, 2022). "For example, this happens for the mitophagy regulator BNIP3, which exerts tumor promotion in melanoma and pancreatic cancer; meanwhile, it is protective against breast cancer." (PMID 34830777, 2021). "BNIP3 can delay the progression of primary breast cancer by preventing the accumulation of dysfunctional mitochondria and reducing the resulting excess reactive oxygen species (ROS)." (PMID 33602168, 2021). "FTO can also target and remove the m6A modification of the 3-‘UTR of BNIP3, resulting in degradation of BNIP3 and subsequent proliferation of the breast cancer cells." (PMID 33926508, 2021). "For example, in colorectal carcinoma, SOX2 promotes cancer through methylation catalyzed by METTL3, while in breast cancer, BNIP3 promotes the cancer through demethylation catalyzed by FTO." (PMID 34489709, 2021). "In breast cancer, a YTHDF2-dependent mechanism underlies the degradation of the BCL2 interacting protein 3 (BNIP3) mRNA, which would otherwise encode an apoptosis-promoting protein that is a downstream target of FTO-mediated m6A modifications." (PMID 34105069, 2021). "FTO has been involved in the tumor progression of breast cancer via suppressing BCL2 interacting protein 3 in an m6A-dependent way." (PMID 34076564, 2021). "For example, in CRC, SOX2 plays a cancer-promoting role through METTL3-catalyzed methylation, while in breast cancer, BNIP3 plays a cancer-promoting role through FTO-catalyzed demethylation." (PMID 32398132, 2020). "Niu et al20 found that the m6A demethylase fat mass and obesity‐associated protein (FTO) promoted proliferation, colony formation and metastasis of human breast cancer cells; BNIP3 is a downstream target of FTO‐mediated m6A modification." (PMID 33098220, 2020). "FTO-induced demethylation of the tumor suppressor BNIP3 mRNA in its 3'UTR causes degradation of the transcript thus eliminating the tumor suppressive effect of BNIP3 in breast cancer." (PMID 32194861, 2020). "BNIP3 has an anticancer effect and is negatively correlated with the expression of the m6A demethylase FTO in breast cancer; BNIP3 can slow down the growth and metastasis of FTO-overexpressing tumors." (PMID 32547955, 2020). "The production of BNIP3 protein has been reported to be upregulated in lung, prostate, glioblastoma multiforme, cervical tumors, endometrial cancer, breast carcinomas, and gastric adenocarcinomas." (PMID 33207677, 2020). "Hypoxia-induced autophagy and/or cell death through BNIP3 was also described for glioma and breast cancer cells." (PMID 30949212, 2019). "FTO dramatically promoted breast cancer cell proliferation, colony formation and metastasis through epigenetically down-regulating BNIP3." (PMID 30922314, 2019).
breast cancer (continued). "As a functional target of FTO, BNIP3 is required for cell apoptosis, suggesting its role as tumor suppressor in breast cancer." (PMID 30922314, 2019). "For example, the pro-mitophagic receptor BNIP3 has tumor suppressor functions in breast cancer, whereas it is thought to have a tumor promoter role in melanoma, renal cell carcinoma and pancreatic cancer." (PMID 31121959, 2019). "FTO promoted breast cancer cell proliferation, colony formation and metastasis by reducing BNIP3 methylation and promoting BNIP3 degradation." (PMID 31801551, 2019). "Our analysis of R2 datasets revealed that BNIP3 levels are positively correlated with overall survival of patients with breast cancer treated with taxane-anthracycline (P-value = 0.035), and with Tamoxifen (P-value = 0.026)." (PMID 30922314, 2019). "Mechanistically, FTO reduced apoptosis of breast cancer cells at least partially via downregulating expression of BNIP3, a pro-apoptosis gene." (PMID 30922314, 2019). "The known function in breast cancer, and BNIP3’s relationship with hypoxia signaling provides a foundation to investigate the role in CRC." (PMID 31671556, 2019). "In hypoxic breast cancer cells, BNIP3-mediated autophagy activation and elevation of amino acid levels were notable." (PMID 31078780, 2019). "In this study, we have developed recombinant measles virus armed with BNiP3, a pro-apoptotic gene of human origin, as an oncolytic agent, and have demonstrated its ability to induce apoptosis in breast cancer cells in vitro." (PMID 30697531, 2018). "As a result, an increased ceramide level can activate apoptosis by enhancing the expression of the pro-apoptotic protein Bcl2 which interacts with protein 3 (BNIP3), as reported in breast cancer cells." (PMID 29588626, 2018). "This is in line with observations that BNIP3 is found mainly in the cytoplasm in invasive human breast cancer cells, while in healthy cells BNIP3 is predominantly localized to the nucleus." (PMID 30250843, 2018). "This cytoplasmic expression has clinical efficacy due to the fact that there have been clinical reports linking downregulation and nuclear expression of BNiP3 to increased potential of metastasis in breast cancer patients." (PMID 30697531, 2018). "BNIP3 is upregulated in breast cancer, lung cancer, and follicular lymphomas, whereas BNIP3 is not expressed in gastric cancer, colorectal cancer, and pancreatic cancer." (PMID 28968982, 2017). "The inhibition of FASN can induce apoptosis in breast cancer cells through upregulating pro-apoptotic genes BNIP3, DAPK2, and TRAIL." (PMID 29093680, 2017). "The mRNA levels of BNIP3 also were markedly up-regulated in DTC compared to mammary tumor cell line." (PMID 27105499, 2016). "BNIP3 expression also was up-regulated in DTC tumors compared to mammary tumors as well as the hypoxia-regulated miRNA, miR-210." (PMID 27105499, 2016). "This experiment showed that the combination of YCW1 and IR significantly inhibited BNIP3 and induced autophagic cell death in an orthotopic breast cancer model." (PMID 27286975, 2016). "Consistently, BNIP3 knockdown in the 4T07 orthotopic mammary tumor model promoted tumor growth and metastasis." (PMID 25810907, 2015). "Expression of p62, LC3A, LC3B, and BNIP3 in stromal cells in breast cancer was reported in a previous study." (PMID 25140630, 2014). "Tumoral LC3A expression was higher in AR-negative breast cancer, while tumoral BNIP3 was higher in AR-positive breast cancer." (PMID 25140630, 2014). "Tumoral LC3A was most highly expressed in AR-negative breast cancers, while tumor BNIP3 was highest in AR-positive breast cancers." (PMID 25140630, 2014). "Our results show that treatment of hypoxic MCF7 and MDA-MB-231 breast cancer cells with the V-ATPase inhibitor Baf1A activated Bnip3-dependent cell death." (PMID 24811485, 2014). "Tumoral LC3A expression was highest in AR-negative breast cancer, while tumoral BNIP3 was highest in AR-positive breast cancer." (PMID 25140630, 2014).